GLI1 (GLI family zinc finger 1)
Diseases named in the same sentence as GLI1 in open-access papers (continued):
Sharing a sentence is not in itself a finding about the gene and the disease.
breast tumor (16 papers, 2009 to 2024). "Studies have shown that the expression of GLI1 along with GLI1, 2 and 3 protein levels are upregulated in breast tumor compared to normal tissue." (PMID 33179013, 2020). "Significant over expression of SHH (R.E = 4.4 ± 3.32), DHH (R.E = 4.7 ± 3.46), PTCH1 (R.E = 3.4 ± 3.08) and GLI1 (R.E = 3.8 ± 2.49) were detected in the breast tumour biopsies as compared with controls." (PMID 29329585, 2018). "We evaluated primary breast tumors from patients for their expression of Merlin and GLI1 by immunohistochemistry." (PMID 28112165, 2017). "The genistein treatment significantly decreased the Smo-positive and Gli1-positive staining in breast tumor tissues, compared with the control group." (PMID 24331293, 2013). "Subsequently we compared GLI1 expression data to previous data on the expression of SHH in the same collective of breast tumours." (PMID 19706168, 2009). "Intensities of nuclear GLI1 protein varied strongly between the different breast tumours as IRS values detected on the TMA ranged between 2 and 12 (3.1% and 24.6% of all analysed tumours, respectively)." (PMID 19706168, 2009). "Therefore, GLI1 inhibitors are potentially efficacious against human breast tumors arising via multiple oncogenic mechanisms." (PMID 36046646, 2022). "Interestingly, neuropilin 2 (NRP2) signaling increased GLI1 expression in breast tumor initiating cells, with GLI1 also inducing BMI-1, a key stem cell factor, and NRP2 expression, establishing an autocrine loop." (PMID 27689403, 2016). "Similarly, GLI1 increased BMI-1 expression in the NRP2low population of cells isolated from human breast tumours." (PMID 23436775, 2013). "Interestingly the results from our statistical analyses showed a significant association between GLI1 overexpression and the presence of Hh member SHH in human breast tumours." (PMID 19706168, 2009). "Interestingly we found a positive significant association between increased nuclear GLI1 expression and tumour stage, lymph node status of the analysed breast tumours supporting a role of GLI1 as a new prognostic marker." (PMID 19706168, 2009). "Similarly in breast tumor cells, osteopontin may activate the hedgehog pathway and enhance drug resistance through GLI1-dependent regulation of ABCB1 and ABCG2." (PMID 27400751, 2016). "GLI1 depletion in SUM1315 NRP2high cells and in the NRP2high population sorted from breast tumour specimens reduced FAK activation." (PMID 23436775, 2013). "We have determined that breast tumor cells have an activated Hh pathway characterized by upregulation of the ligand, IHH and transcription factor GLI1." (PMID 22479615, 2012). "Regarding the clinical impact of increased GLI1 protein expression on breast tumour recurrence the derived data were statistically not significant (P = 0.102)." (PMID 19706168, 2009). "However overexpression of GLI1 in the analysed breast tumours was statistically not significant (P = 0.251, two-tailed Mann-Whitney U-test)." (PMID 19706168, 2009). "Gli1 and ALDH1 protein expression levels were low or undetectable in the 10 normal samples (data not shown) but comparatively high in breast tumor tissues." (PMID 24889938, 2014). "To validate the existence of the proposed pathway in clinical specimens, we quantified the expression of VEGF, NRP2 and GLI1 in 32 TPN and 35 non-TPN human breast tumour specimens by qPCR." (PMID 23436775, 2013). "The issue of whether GLI1 is induced by canonical or non-canonical Hh signalling in our models was addressed initially by examining the expression of Patched and Smoothened in both SUM1315 and the cells that we isolated from human breast tumours." (PMID 23436775, 2013).
esophageal cancer (16 papers, 2008 to 2025). A primary or metastatic malignant neoplasm involving the esophagus. "It has been reported that hedgehog pathway regulated esophageal homeostasis, and was activated in partial esophageal cancer and high GLI1 level correlates with poor prognosis." (PMID 41497797, 2025). "The HH pathway and associated overexpression of GLI1 have been reported as oncogenic while the nuclear expression of GLI1 is considered predictive of a pathologic complete response to chemoradiation in esophageal cancer (EC)." (PMID 32913560, 2020). "Gli1 expression also significantly correlates with stemness characteristics of esophageal carcinoma." (PMID 32430068, 2020). "PI3K/AKT and MEK/ERK pathways cooperate with Hh at the level of Gli1 to promote proliferation and survival of esophageal cancer cells." (PMID 30463396, 2018). "Target hedgehog‐GLI1 pathway can be a powerful therapy strategy for esophageal cancer." (PMID 41497797, 2025). "GLI1 expression is significantly upregulated in esophageal cancer cell lines." (PMID 38020914, 2023). "Previous studies have reported aberrant activation of HH/GLI signaling in esophageal cancer, which can be caused by a number of factors including genetic alterations of individual pathway components, such as PTCH or SMO mutations and GLI1/2 amplification." (PMID 32913560, 2020). "In summary, we showed that the monoclonal amplification of Gli-1 nuclear localisation implicating Hh pathway activation was correlated with oesophageal cancer progression, and that subtle Hh cascade activation after CRT indicated early cancer progenitor cell emergence." (PMID 18475300, 2008). "In esophageal cancer, mTOR can activate GLI1 phosphorylation (at Ser84) through S6K1, leading to the dissociation of GLI1 from SUFU and increasing its transcriptional activity." (PMID 37919751, 2023). "In esophageal cancer, mTOR signaling promotes Hh signaling through S6K1-mediated Gli1 phosphorylation at Ser84, which releases Gli1 from its repressor Sufu." (PMID 35186941, 2022). "In a second model of esophageal cancer, activated mTOR/S6K1 was shown to phosphorylate Gli1, that consequently releases SUFU, and activates Gli1 target gene transcription, enhancing oncogenic function." (PMID 30463396, 2018). "Furthermore, a cross-talk between the two pathways has been described in a model of esophageal cancer where mTORC1/S6K1 promotes the oncogenic function of GLI1, through S6K1-mediated phosphorylation of GLI1, in a SMO-independent manner." (PMID 29396625, 2018). "There are no reported data on the role of Gli-1 expression, which is a key Hh pathway target, in oesophageal cancer progression after CRT." (PMID 18475300, 2008). "As data were not available on the role of Gli-1 expression in oesophageal cancer progression, we analysed whether it could be used to predict disease progression and prognosis in oesophageal cancer patients undergoing neoadjuvant chemoradiotherapy (CRT)." (PMID 18475300, 2008).
leukemia (16 papers, 2015 to 2025). A malignant (clonal) hematologic disorder, involving hematopoietic stem cells and characterized by the presence of primitive or atypical myeloid or lymphoid cells in the bone marrow and the blood. "Relevant for MPM, where a subset of patients show Hedgehog signalling activation, editing of mRNA encoding for glioma-associated oncogene 1 (GLI-1) results in increased Gli-1 protein stability and maintains tumour initiating cells in leukaemia." (PMID 33050791, 2020). "These in vivo data suggested that EZH2 inhibition by chidamide or shEZH2 decreased leukemia growth and increased the antileukemia effect of adriamycin through suppression of Smo/Gli-1 pathway in the leukemia-bearing mouse models." (PMID 33743723, 2021). "Our findings may have therapeutic relevance, as inhibition of AMPK by Compound C sensitizes leukemia cells to the cytotoxic effects of the GLI1/2 inhibitor GANT-61 in vitro." (PMID 34203724, 2021). "The concurrent targeting of Gli1 and Akt pathways represents a rational and promising strategy to overcome intrinsic or acquired resistance associated with Hedgehog inhibition, particularly in leukemias characterized by non-canonical Hedgehog activation." (PMID 41439992, 2025). "It was demonstrated that SHH and GLI1 are expressed in leukemic cell lines and primary leukemic blasts, and recent evidence suggests that inhibitors of the Hh pathway could be effective in reverting leukemia chemoresistance." (PMID 25861282, 2015). "The Hedgehog signaling pathway is required to maintain the leukemic stem cell population; therefore, glasdegib binding and SMO inhibition reduce AML levels of GLI1 and AML leukemia initiation potential." (PMID 39001536, 2024). "Our previous studies showed that EZH2 overexpression and activation of Smo/Gli-1 pathway were related to the poor prognosis in AML patients, and Smo inhibitor effectively decreased leukemia growth and increased chemosensitivity." (PMID 33743723, 2021). "Although GLI1/2 are not activated in response to HH in A549 cells, both HH and WNT signaling could be activated in other NSCLC cell lines, or in other types of tumors (e.g., BCC, CRC and leukemia)." (PMID 35908024, 2022).
lung adenocarcinoma (16 papers, 2013 to 2025). A carcinoma that arises from the lung and is characterized by the presence of malignant glandular epithelial cells. "Surprisingly, the mRNA levels of SHH and GLI1 were markedly upregulated in lung adenocarcinoma tissues with EGFR mutations (P < 0.0001 and P = 0.048, respectively)." (PMID 39721017, 2025). "In a study of advanced lung adenocarcinoma, GLI1 mRNA and GLI3 mRNA expression were associated with lower 5-year survival rates in patients." (PMID 38498906, 2024). "In lung adenocarcinoma, the presence of Shh and Gli-1 correlated with better overall survival, showing association with EGFR overexpression, whereas TGF-ß acts as a tumor promoter by transcriptionally inducing Gli-proteins and thus mediating tumor survival." (PMID 27918595, 2016). "Our experiments revealed that SH regulated the Hedgehog signaling pathway in lung adenocarcinoma by downregulating the protein levels of the Hedgehog pathway nuclear transcription factor Gli1 and the Hedgehog pathway key factors SHh, Ptc, and Smo." (PMID 41444284, 2025). "A recent study reported that 76% of lung adenocarcinoma patients express GLI1, the amplifier of the pathway." (PMID 34771484, 2021). "We identified significant (p≤0.05) quantitative enrichment in domain 3 compared to domain 6 of the GLI-1 gene promoter, including in the lung adenocarcinoma cell lines A427 and A549." (PMID 28978016, 2017). "Here, we report the Gli activation in two cohorts of patients with lung adenocarcinomas and show that Gli1 and EMT markers are inversely correlated in lung adenocarcinoma." (PMID 27533453, 2016). "Subset analysis of patients with stage III-IV lung adenocarcinoma (n = 71) showed significantly worse clinical outcomes in both the higher GLI1 and GLI3 mRNA expression groups." (PMID 25103784, 2014). "In clinical samples, immunohistochemical analysis of tissue microarray have revealed significant correlation among the Hh molecules in early-stage NSCLC and of lymph node metastasis with nuclear GLI1 immunolocalization in lung adenocarcinoma." (PMID 25103784, 2014). "The present study also provides evidence of the capacity of GLI3 to activate Hh signaling in concert with GLI1 in advanced lung adenocarcinoma." (PMID 25103784, 2014). "Besides this, GLI1 also supports the EMT process leading to resistance to EGFR-TKIs in EGFRm lung adenocarcinoma." (PMID 34771484, 2021). "To assess whether GLI1 plays a role in lung adenocarcinoma, we generated a GLI1 gene expression dataset from the TCGA LUAD database of 577 patients." (PMID 31783569, 2019). "To confirm this hypothesis, we quantitatively validated the MEOX2 occupancy of GLI-1 gene promoter sequences in 13 lung samples from patients with adenocarcinoma and in the lung adenocarcinoma cell lines A427 and A549." (PMID 28978016, 2017). "Interestingly, some lung adenocarcinoma samples showed relatively high GLI1 and GLI3 mRNA expression, and their expression patterns were considerably correlated." (PMID 25103784, 2014). "Furthermore, an inducible, cisplatinum dose-dependent MEOX2 protein expression pattern was identified in lung adenocarcinoma cells, corresponding to cisplatinum-induced GLI-1 protein expression in the lung adenocarcinoma cell lines A427 and A549 that was markedly reduced by anti-MEOX2 siRNAs." (PMID 28978016, 2017). "Moreover, a previous report showed that GLI1 upregulated expression of the embryonic stem cell transcription factor SRY- (sex determining region Y-) box 2 (SOX2) by cooperation with EGF signaling in lung adenocarcinoma-derived cell lines." (PMID 28105432, 2016). "We then utilized the GEPIA2 online platform to examine the correlation among the mRNA levels of SHH, GLI1, DUSP13B, and STAT3 in lung adenocarcinoma tissues from the TCGA dataset." (PMID 39721017, 2025). "GLI1 expression in the pathological stage of the LUAD dataset demonstrated that GLI1 is elevated in stage II and III lung adenocarcinoma compared with stage I and IV lung adenocarcinoma." (PMID 31783569, 2019).
lung adenocarcinoma (continued). "A549 lung adenocarcinoma cells that obtain mesenchymal phenotype (A549-M cells) show upregulated SHH ligand and GLI1 expression compared with A549 cells." (PMID 28105432, 2016). "We found that GLI1, GLI2, and GLI3 mRNA were expressed in almost all advanced stage lung adenocarcinoma tissue samples, and strong correlation was observed between GLI1 and GLI3 mRNA expression." (PMID 25103784, 2014). "The levels of GLI1, GLI2, and GLI3 mRNA expression were measured by quantitative real-time polymerase chain reaction in surgically obtained tissue samples from stage II-IV lung adenocarcinoma patients (n = 102)." (PMID 25103784, 2014). "However, survival analysis of only lung adenocarcinoma patients with EGFR-non-mutated status identified poorer overall survival (statistically significant at p≤0.005) with higher MEOX2 and GLI-1 protein co-expression levels (p=0.045 and p=0.006, respectively)." (PMID 28978016, 2017). "Interestingly, some GLI1/GLI3 highly expressing tumors (in this cohort, defined as the upper 15th percentile of patients for each mRNA expression) showed significantly poorer patient prognosis in advanced lung adenocarcinoma." (PMID 25103784, 2014). "As we found considerable impact of GLI1 and GLI3 gene expression on patient survival, this study demonstrates that inhibition of Hh signaling may be a promising drug target for the treatment of advanced lung adenocarcinoma." (PMID 25103784, 2014). "Although a statistically significant negative correlation between survival and GLI1 expression has been shown in breast, esophageal, colorectal, and bladder cancers, this is the first study to demonstrate a clinical impact of GLI1 on patient survival in lung adenocarcinoma." (PMID 25103784, 2014). "From our research, no relation between GLI2 mRNA expression and GLI1 mRNA level, GLI3 mRNA level, or patient survival was detected, thus, the role of GLI2 in the pathogenesis of lung adenocarcinoma is still unclear." (PMID 25103784, 2014). "Cellular migration and proliferation were systematically analyzed in functional assays, and significant (p≤0.001) MEOX2-dependent GLI-1 protein expression was present in A549 cells, which contrasted with non-detectable MEOX2 levels in the H1975 lung adenocarcinoma cell line." (PMID 28978016, 2017).
non-small cell lung carcinoma (16 papers, 2009 to 2025). A group of at least three distinct histological types of lung cancer, including non-small cell squamous cell carcinoma, adenocarcinoma, and large cell carcinoma. "RACK1 promotes the progression and metastasis of non-small cell lung cancers that primarily involve activation of the Shh pathway, in which RACK1 interacts with activated Smo to initiate Gli1 transcription in non-small cell lung cancer cells." (PMID 29899399, 2018). "By comparison on the mRNA levels of Set7 and Gli1 between Beas2B, a normal bronchial epithelial lung cell line, and A549, a non-small cell lung cancer cell line, we found that both Set7 and Gli1 were extensively expressed in A549 cells." (PMID 27146893, 2016). "Evidently, p70S6K2 inhibited GSK3β function by phosphorylating its Ser9 residue, which in turn stabilized GLI1 protein levels and enhanced cell viability/proliferation of non-small cell lung cancer cell lines, and this effect can be reversed upon p70S6K2 silencing." (PMID 34572373, 2021). "Interestingly, the SHH-induced transcription factor GLI1, which is known for its involvement in stem cell renewal in non-small cell lung cancer, localized to the nuclei of most KRT5+ cells in the distal IPF lung, arguing for activation of the SHH pathway in these cells." (PMID 27423691, 2016). "For instance, GLI1-mediated regulation of SOX2 enhances CSC self-renewal and confers resistance to EGFR inhibitors in non-small cell lung cancer." (PMID 33958721, 2021). "The downregulation of Gli1 expression and transcriptional activity also mediates some effects of metformin in LKB1-wild type non-small cell lung cancer (NSCLC) cell lines." (PMID 34884872, 2021). "In non-small cell lung cancer (NSCLC), blocking SMO and GLI1 induced autophagy and apoptotic responses." (PMID 26988232, 2016). "Moreover, experimental studies indicate that the MEOX2 and GLI-1 transcription factors can influence the genetic expression of EGFR, a key driver gene of non-small cell lung carcinomas (NSCLC), by modulating specific histone marks on its enhancer and promoter sequences." (PMID 39971779, 2025).